IL6 (interleukin 6)
Diseases named in the same sentence as IL6 in open-access papers (continued):
Sharing a sentence is not in itself a finding about the gene and the disease.
COVID-19 (continued). "Although there are no direct assessments that NETs contribute to the cytokine storm in the respiratory failure in patients with severe COVID-19, although evidence indicates that proinflammatory cytokines, such as IL-1β and IL-6, are closely linked to NET production during severe infection." (PMID 36439786, 2022). "In many studies on COVID-19, IL-6 has been proved to be associated with interstitial lung disease." (PMID 36199667, 2022). "The changes of iron metabolism markers in blood samples (including decreased serum iron, and increased ferritin) demonstrated iron overload and are associated with severe COVID-19.241–244 The secretion of IL-6 is highly induced by inflammation upon SARS-COV-2 infection." (PMID 35697684, 2022). "Moreover, dynamic variations of IL-6 have been associated with the survival of severe COVID-19 patients admitted to the ICU." (PMID 36142336, 2022). "Evidence suggests that the severity of COVID-19 is generally associated with a cytokine storm, primarily driven by the pro-inflammatory cytokines—IL-6, IL-8 and TNF-α, the overproduction of which leads to impaired oxygen diffusion, pulmonary fibrosis and multi-organ failure." (PMID 35456990, 2022). "In addition, inhibition of interleukin (IL)-6 with dexamethasone, tocilizumab, and sarilumab effectively treats cytokine storm and significantly reduces mortality caused by COVID-19." (PMID 35454970, 2022). "Because IL-6 is implicated in the pathological conditions and severity of COVID-19, we decided to perform a literature search to find an approved drug that would inhibit the expression/secretion of this interleukin and the number of monocytes and macrophages infiltrating the lungs." (PMID 35744777, 2022). "However, exaggerated and excessive synthesis of IL-6 accounts for its elevated serum levels in COVID-19 patients and is associated with disease severity due to its ability to recruit different cell immunotypes in innate immune response." (PMID 35843719, 2022). "According to a recent study, patients with moderate or severe COVID-19 mainly developed mild-to-severe pulmonary fibrosis, and the severe lung inflammation (IL-6 levels in the acute stage) has been associated with more extensive and severe residual pulmonary fibrosis." (PMID 35496055, 2022). "Considering our previous results, the aim of this study was to evaluate the relationship between the presence of SARS-CoV-2 viremia and the time evolution and IL6 levels in a prospective cohort of COVID-19 hospitalized patients." (PMID 35783606, 2022). "Finally, laboratory biomarkers, such as elevated ferritin or interleukin-6 levels, have already been identified as risk factors for a significantly worse prognosis in COVID-19 patients." (PMID 35683347, 2022). "The findings reported herein suggest that IL-6 may play a role in the increased risk of severe COVID-19 in PDM individuals." (PMID 35898449, 2022). "Moreover, Interleukin 6 (IL-6) and IFNγ can reduce the incidence, severity, and risk of death from infections such as COVID-19." (PMID 36293182, 2022). "Moreover, COVID-19 is associated with a high inflammatory state and cytokine storm characterized by high levels of pro-inflammatory cytokines such as IL-1β, IL-6, and monocyte chemoattractant protein-1 (MCP-1)." (PMID 36420258, 2022). "Higher serum IL-6 levels were also a risk factor for AKI in COVID-19 patients in another study." (PMID 35656097, 2022). "The relevance of these anti-inflammatory properties to COVID-19-induced immunopathologies is further highlighted by the accumulating evidence showing association of markedly elevated levels of IL-6 and other pro-inflammatory cytokines in patients with severe COVID-19 clinical outcomes." (PMID 35615359, 2022). "Among the interleukins, IL-6 – a pleiotropic, proinflammatory cytokine produced by several cells like lymphocytes, monocytes and fibroblasts, is of major significance owing to its pleiotropic effects, and it has been linked to COVID-19 severity." (PMID 36415655, 2022).
COVID-19 (continued). "In addition, adipose tissue is an initial source of interleukin-6 (IL-6), an independent risk factor in determining the severity of COVID-19 in a patient." (PMID 35711466, 2022). "Severe coronavirus disease 2019 (COVID-19) has been linked to dysregulated immune responses, including an excessive inflammatory response marked by high levels of proinflammatory cytokines such as interleukin-6 (IL-6)." (PMID 35295598, 2022). "Furthermore, NHP models have inflammatory cytokines such as IL-6, which remain elevated into the post-acute phase, parallel to high systemic IL-6 levels in humans associated with severe COVID-19." (PMID 36070309, 2022). "In conclusion, this study showed that an IL-6 LFA test strip combined with a spectrometric reader could provide a promising POC diagnostic approach for early recognition of COVID-19 patients who are at risk for acute respiratory failure." (PMID 35242747, 2022). "Post-acute sequelae of COVID-19, also called Long-COVID, is as HF potentially caused by incomplete resolution of inflammation and characterized by a long lasting elevation of IL-1β, IL-6 and TNF-α." (PMID 35548445, 2022). "TCZ should only be used in cases with identified cytokine storm, with IL-6 levels exceeding 100 pg/mL and features of COVID-19 associated pneumonia; however, data on its efficacy in the group of the patients with precisely identified severe disease are limited." (PMID 35566412, 2022). "Results of the present study, with all potential limitations derived from an in vitro study, suggest that IL-6 might play a pivotal role in the potential pathophysiological scenario in which COVID-19 causes thrombosis." (PMID 35050236, 2022). "IL-6 is an important marker of inflammation, and just as its relationship with many other diseases has been investigated, so there are also many recent studies showing an association with COVID-19." (PMID 35685514, 2022). "For example, in RA, anti-TNFα reduces the production of additional cytokines such as IL-1 and IL-6; therefore, blocking TNFα in COVID-19 could reduce these potentially pathogenic cytokines." (PMID 36579506, 2022). "During the COVID-19 pandemic's infancy, studies of infected patients reported findings of elevated levels of proinflammatory cytokines (e.g., IL-1, IL-2, IL-6, IL-12, IL-18, and TNF-α) that eventually cause uncontrolled systemic inflammation and multiorgan damage." (PMID 35845297, 2022). "In this regard, probably some of the reasons why this has been limited are because it has been reported that COVID-19 patients display variable levels of IL-6, and the association of secondary infections with immunomodulators such as tocilizumab also is a common risk that has been identified." (PMID 35631442, 2022). "Other genes commonly implicated in coronavirus disease 2019 include ACE2, IL6, DPP9, TYK2, TMPRSS2, FOXP4, and TNF, while the emerging genes consist of FURIN, CXCL10, OAS1, OAS2, OAS3, and ISG15." (PMID 35454970, 2022). "Previous studies have shown that increased interleukin (IL)-6 and tumor necrosis factor alpha (TNFα), along with T helper 1-specific cytokines such as interferon-induced protein 10 (IP-10), are associated with severe COVID-19 response and mortality." (PMID 36865568, 2022). "Similarly, the NSP9 and NSP10 proteins of SARS-CoV-2 induce overproduction of IL-6 and IL-8, which are the leading causes of cytokine storm leading to death in COVID-19 patients." (PMID 35273506, 2022). "Moreover, pulmonary sequelae of COVID-19 have been associated with IL-6 and TGF-beta via provocation of a fibrotic state." (PMID 36121875, 2022). "Validation to these findings was observed during the recent COVID-19 pandemic, in which NK cells derived from severe COVID-19 patients, compared to healthy patients showed reduced expression of granzyme A that was associated with IL-6 serum levels, in addition to reduced perforin expression." (PMID 33815404, 2021).
COVID-19 (continued). "We consecutively included patients during the first peak of the COVID-19 epidemic in Brazil and analyzed the expressions of genes encoding interleukin (IL)-1β, IL-6, IL-8, IL-10, IL-12A, IL-12B, and tumor necrosis factor-α in peripheral blood mononuclear cells." (PMID 33819170, 2021). "Notably, interleukin (IL)-6, an inflammatory cytokine that was found associated with more adverse clinical outcomes for COVID-19,38 was 3.5 times higher in the pregnant patients." (PMID 34326311, 2021). "Animal models, particularly with humanized ACE2 transgenic mice, could determine if auranofin has the potential to reduce SARS-CoV-2-associated IL-6-derived pathogenicity and decrease COVID-19 immunopathology." (PMID 34630379, 2021). "Nevertheless, the concept of immune-mediated myocarditis could be supported by the fact that IL-6 was significantly associated with the pre- and postmanagement changes of cTnI levels in a recent case report of COVID-19 complicated with fulminant myocarditis." (PMID 33815838, 2021). "In several reports, 21,22 higher levels of IL-6 were found in the non-survivors, and this data may show the association between the severity of the COVID-19 and IL-6 levels." (PMID 35283947, 2021). "A screen for candidate agents revealed that IL-6 and IL-18 may individually contribute different facets of these COVID-19–linked perturbations." (PMID 34433692, 2021). "Moreover, adiposity is associated with higher levels of local and systemic inflammation markers, such as interleukin-6 and C-reactive protein, which have been positively correlated with COVID-19 susceptibility and severity." (PMID 34959805, 2021). "Accordingly, recent data on the ratio of the pro-inflammatory cytokine IL-6 and the anti-inflammatory cytokine IL-10 suggested that serum cytokines may be used for risk stratification in hospitalized COVID-19 patients." (PMID 34540715, 2021). "Furthermore, several studies reported increased IL-6 serum levels to be a hallmark of COVID-19, but also TNF and IL-8." (PMID 33441124, 2021). "In human cases of COVID-19, elevated levels of IL-6 have been associated with severe disease." (PMID 34424943, 2021). "It has been demonstrated that increased levels of IL-6 from 6 hours until ≥18 days post-COVID-19 symptom onset, is associated with poor prognosis, whereas its gradual increase within 3-5 days, and its return to normal levels after 15-17 days, is linked to good prognosis." (PMID 35126355, 2021). "Additionally, the occurrence of cytokine storms has been associated with critically ill COVID-19 patients, resulting in elevated levels of interleukin 6 and C-reactive protein; both have been associated with increased risk of stroke." (PMID 34574386, 2021). "COVID-19 patients who succumb to pneumonia and hypoxia had one hallmark feature of the profound inflammatory state that marked elevation of serum inflammatory cytokines (IL-6, IFN-γ, IL-1β, TNF-α and TGF-β) and chemokines (CCL2, CCL5, CXCL8 and CXCL10)." (PMID 34313585, 2021). "Increased procalcitonin level in COVID-19 patients may be associated with the release of some cytokines, especially IL-6." (PMID 33868645, 2021). "IL-6 may play a proinflammatory role in pulmonary inflammation, and a significant increase in IL-6 level was found in the majority of patients, suggesting that severe COVID-19 may cause a significant exudation of IL-6 into the lungs." (PMID 34122618, 2021). "In patients with COVID-19, systemic production of IL-6 is associated with disease progression." (PMID 34452537, 2021). "Our results suggest that CATi is an individual predictor of risk of COVID-19 severity and early death as it represents the cardiovascular reservoir of both virus entry and pro-inflammatory cytokine release whereas IL-6 is an instantaneous measure of the systemic inflammation level." (PMID 34384426, 2021).
COVID-19 (continued). "The epigenetic properties ACE2 and IL-6 genes may serve as biomarkers to longitudinally predict COVID-19 susceptibility in vertebrates and partially explain COVID-19 inequality in people of different subgroups." (PMID 33503821, 2021). "Therefore, IL-6 inhibition looks like an attractive therapeutic strategy in order to attenuate the dramatic consequences of COVID-19-associated cytokine storm." (PMID 33802761, 2021). "In COVID-19, the levels of IL-6 are associated with pulmonary complications and death." (PMID 34456928, 2021). "In addition, the cytokines implicated in severe COVID-19 pathogenesis, such as IL-1 and IL-6, have been proposed to be potential therapeutic targets." (PMID 34360616, 2021). "When considering the role of cytokines in COVID-19 specifically, it has been observed that higher levels of IL-6, IL-8 and TNF, at the time of admission, were associated with significantly lower rates of survival after adjusting for demographics and comorbidities as confounding variables." (PMID 34341776, 2021). "Due to the virus contact with gustatory or olfactory, the COVID-19 patients showed cranial nerve symptoms such as hyposmia and dysgeusia, which might be caused by elevated IL-6 in saliva, plasma, and nasal mucus." (PMID 34577633, 2021). "An increased serum level of IL-6 had been reported to be linked with increased COVID-19 fatality." (PMID 33078369, 2021). "Besides, levels of IL-6 are reported to be linked with the increased need for incubation and mechanical ventilation of COVID-19 patients." (PMID 34538093, 2021). "Previous studies have shown that elevated levels of proinflammatory cytokines, such as IFN-γ, TNF-α, IL-6 and IL-8, are associated with severe lung injury and adverse outcomes, suggesting that the magnitude of cytokine storm is associated with COVID-19 severity." (PMID 34829345, 2021). "Chronic low-grade inflammation is associated with prolonged exposure to IL-6 signaling, which may contribute to the progression of COVID-19 in older patients." (PMID 34112103, 2021). "Moreover, absolute cTn levels became significantly elevated in patients who ultimately died due to COVID-19, and this was also associated with a baseline increase in CK-MB, IL-6, and hs-CRP." (PMID 33815838, 2021). "Based on our comparison results, hypertension and cardiovascular and cerebrovascular diseases were closely associated with disease progression in COVID-19 patients, which could be linked with the increased level of IL-6." (PMID 34123873, 2021). "Of note, interleukin-6 (IL-6) is proposed to be associated with the severity of COVID-19." (PMID 34831321, 2021). "High levels of hallmark cytokines associated with SARS-Cov2 infection such as CXCL10 and IL-6 could be detected in the nasal cavity of patients with mild COVID-19." (PMID 34581925, 2021). "Among the stress cytokines responding to DAMP(s) IL-6 plays a prominent role in the pathogenesis of overwhelming cytokine production in both severe COVID-19 and advanced aGvHD cases – the cytokine storm which causes the dysregulation of the immune system and deepens immunosuppression." (PMID 34149697, 2021). "Herein, elevated levels of TNF and IL-1β as acute phase response cytokines and higher IL-8 and MCP-1 levels can cause a facilitated increase of IL-6 levels (which, in COVID-19 subjects, is considered as a main intermediary of viral cytokine storm and inflammation)." (PMID 34195193, 2021). "Increased expression of IL6 was associated with severity in COVID-19, and corticosteroids such as dexamethasone and prednisone or methylprednisolone downregulated IL6 and showed positive clinical outcomes in patients with severe COVID-19." (PMID 34067609, 2021). "The severity and mortality of COVID-19 patients are associated with substantial mononuclear cell infiltration in their lungs and other organs, along with elevated levels of circulating cytokines and chemokines including IL-6, TNF and CXCL10." (PMID 34073047, 2021).
COVID-19 (continued). "COVID-19 patients with HOMA-IR > 3 had significantly elevated levels of IL-6 and ferritin, which could be linked to a chronic inflammatory state in this group." (PMID 34680053, 2021). "The presumed elevations in IL-6 concentrations have been hypothesized as causal in severe COVID-19 and this has led to interventional trials testing therapies that block IL-6." (PMID 33874973, 2021). "Elevated pro-inflammatory cytokines such as interleukin-6 (IL-6) and C-reactive protein (CRP) have been seen in patients with Coronavirus Disease 2019 (COVID-19) and are associated with worse outcomes." (PMID 33510335, 2021). "In addition to IL6, we have highlighted novel protein markers associated with disease severity in COVID-19 patients and are all involved in the immune system, with many mediating cytokine productions, including IL6." (PMID 33737684, 2021). "The involvement of IL-6 in the cytokine storm was also confirmed by a retrospective, multicenter cohort study that identified several risk factors for the mortality of adult inpatients with COVID-19 in Wuhan, China." (PMID 33499310, 2021). "In patients with fatty liver and obesity, the serum IL-6 level is positively associated with fat content in liver and viscera, and may promote the progression of COVID-19." (PMID 34602072, 2021). "Moreover, increased serum interleukin 6 (IL-6) level has also been reported to be associated with poorer prognosis and higher death rates in COVID-19 patients." (PMID 34643417, 2021). "Furthermore, the present study has suggested that CRS caused by IL-6 is common in COVID-19 patients and is responsible for the severe COVID-19 acute respiratory distress among these patients." (PMID 33146673, 2021). "A low autonomic nervous system activity, i.e. low SDNN or Energy, and a predominance of the parasympathetic system, i.e. low HFnu or ANIm, due to the sympathetic depletion in COVID-19 patients are associated with a worse prognosis, higher mortality, and higher IL-6 levels." (PMID 33760875, 2021). "Anti-IL-6 drugs for COVID-19 are a cause of contention since the outbreak of the global pandemic." (PMID 33244947, 2021). "Heparin has also been implicated in binding to COVID-19 S proteins as well as downregulating IL-6." (PMID 34068127, 2021). "Higher levels of IL-6 have been associated with COVID-19 severity." (PMID 34937570, 2021). "Furthermore, the levels of IL-6 and albumin are independent risk factors for pulmonary fibrosis and should be regarded as important therapeutic targets for the treatment of COVID-19 patients with pulmonary fibrosis." (PMID 33755708, 2021). "In COVID-19 patients with older age, IL-6 is an independent risk factor for in-hospital mortality." (PMID 33907513, 2021). "Interleukin-6 (IL-6) is involved in COVID-19-associated cytokine storm, and several trials investigated whether its inhibition could improve patients’ outcome." (PMID 34704175, 2021). "In addition to the use of corticosteroid therapy, more recent studies of anti-IL-6 therapy have also shown reduced mortality in COVID-19-associated ARDS in general." (PMID 34034789, 2021). "This suggests that interleukin-6-mediated vasopressin release may contribute to COVID-19-associated hyponatraemia." (PMID 34292875, 2021). "Serum cytokine levels that are elevated in patients with COVID-19-associated cytokine storm include IL-1β, IL-6, interferon γ-induced protein-10 (IP-10), TNF-α, interferon-γ (IFN-γ), macrophage inflammatory protein (MIP) -1α and -1β, and vascular endothelial growth factor (VEGF)." (PMID 33807915, 2021). "Strikingly, combined stimulation of anti-spike IgG immune complexes and the toll-like receptor 3 agonist, polyinosinic:polycytidylic acid (poly(I:C)) increased the production of COVID-19-associated pro-inflammatory cytokines IL-1β, IL-6, and TNF compared to IgG or poly(I:C) alone." (PMID 33979301, 2021).